MBD1 (methyl-CpG binding domain protein 1)
Diseases named in the same sentence as MBD1 in open-access papers (continued):
Sharing a sentence is not in itself a finding about the gene and the disease.
gallbladder cancer (2 papers, 2019 to 2020). "Overexpression and deletion in vitro validated MBD1 as a potent oncogene promoting malignant behaviors in gallbladder cancer cells, including invasion, proliferation and migration, as well as epithelial–mesenchymal transition." (PMID 31516389, 2019). "We found that MBD1 expression was significantly upregulated in gallbladder cancer tissues compared with that in surrounding normal tissues according to immunohistochemical analysis of 84 surgically resected gallbladder cancer specimens." (PMID 31516389, 2019). "Herein, our data show that targeting MBD1 restored gallbladder cancer cell sensitivity to gemcitabine chemotherapy." (PMID 31516389, 2019). "As an oncogene, MBD1 promotes cell proliferation and metastasis in gallbladder cancer." (PMID 32469064, 2020). "Taken together, the results of our study revealed a novel function of MBD1 in gallbladder cancer tumor development and progression through participation in the gallbladder cancer epithelial–mesenchymal transition program, which is involved in resistance to gemcitabine chemotherapy." (PMID 31516389, 2019). "However, whether MBD1 is involved in tumorigenesis, especially in gallbladder cancer, is totally unknown." (PMID 31516389, 2019). "Thus, MBD1 may be a potential therapeutic target for gallbladder cancer." (PMID 31516389, 2019).
triple-negative breast carcinoma (2 papers, 2024). An invasive breast carcinoma which is negative for expression of estrogen receptor (ER), progesterone receptor (PR), and human epidermal growth factor receptor 2 (HER2).
Wilson disease (2 papers, 2017 to 2018). A very rare inherited multisystemic disease presenting non-specific neurological, hepatic, psychiatric or osseo-muscular manifestations due to excessive copper deposition in the body. "Out of about 300 single amino acid substitutions known to be associated with Wilson disease, only five are located in the MBD1-4 region, and only one of those five, G85V, in MBD1." (PMID 29330485, 2018). "Our findings imply that reduced stability and enhanced dynamics of MBD1 or MBD6 is the origin of ATP7B dysfunction in Wilson disease patients with the G85V or G591D mutation." (PMID 27744583, 2017). "In summary, introducing a larger amino acid (Asp or Val instead of Gly) at position 386 in MBD4 (as found in MBD1 and MBD6 in Wilson disease patients) results in enhanced domain structural dynamics in silico and decreased resistance towards thermal perturbations in vitro." (PMID 27744583, 2017).
allergic rhinitis (1 paper, 2012). Inflammation of the nasal mucous membranes caused by an IgE-mediated response to external allergens. "The mRNA expression of MBD-1 significantly decreased in both allergic rhinitis (3.44 fold, P = 0.0242) and mev mice (1.79 fold, P = 0.0182)." (PMID 22509389, 2012).
Alpha-thalassemia (1 paper, 2022). Alpha-thalassemia is an inherited hemoglobinopathy characterized by impaired synthesis of alpha-globin chains leading to a variable clinical picture depending on the number of affected alleles. "These genes included laminin subunit beta 1(LAMB1), ATPase Na+/K+ transporting subunit alpha 1 (ATP1A1), alpha thalassemia/mental retardation syndrome X-linked (ATRX), and methyl-CpG binding domain protein 1 (MBD1)." (PMID 36389237, 2022).
Autoimmunity (1 paper, 2022). The occurrence of an immune reaction against the organism's own cells or tissues. "MBD1 has been previously shown to be involved in T cell development (consistent with our above observation that there were T cell differences in some of our CC analyses) and autoimmunity, neural development, and adipocyte differentiation." (PMID 36574452, 2022).
chronic hepatitis B (1 paper, 2019).
Cognitive impairment (1 paper, 2011). Abnormal cognition is characterized by deficits in thinking, reasoning, or remembering. "So far, this is the only Mbd protein reported to be specifically involved in hippocampal neurogenesis; Mbd1 deficient mice, although without noticeable developmental deficits, have reduced NSCs proliferation that correlate with cognitive impairments in spatial memory." (PMID 22414227, 2011).
colitis (1 paper, 2025). Inflammation of the colon. "Similar to I3C, our data showed that TCDD suppressed colitis, which was associated with the induction of mBD‐1." (PMID 40410944, 2025). "Also, treatment of anti‐CD40‐induced colitis mice with I3C caused an increase in the expression of AhR and mBD‐1." (PMID 40410944, 2025). "Also, we observed that the activation of AhR by other AhR ligands such as TCDD, also caused significant upregulation of mBD‐1 and suppressed colitis." (PMID 40410944, 2025). "We next addressed the role of mBD‐1 in colitis‐associated dysbiosis using antibodies against BD1." (PMID 40410944, 2025). "Similar to I3C, our data showed that TCDD upregulated AhR, CYP1A1 and mBD‐1 in CECs from control and colitis (anti‐CD40/ DSS‐ induced) animals." (PMID 40410944, 2025). "To investigate the impact of AhR‐mediated induction of mBD‐1 expression on colitis, we generated conditional AhR knockout mice in vil1‐expressing CECs using the cre‐flox system." (PMID 40410944, 2025). "To further mechanistically characterize the role of AhR and mBD‐1, we extended the human studies in the murine models of colitis." (PMID 40410944, 2025). "Together, these data demonstrated that during colitis, mBD‐1 is downregulated and AhR ligands such as I3C or TCDD can induce the expression of mBD‐1 in CECs." (PMID 40410944, 2025). "Multiple lines of colitis mice models and cell‐based experiments demonstrated that I3C treatment activates AhR, which directly binds to the DREs in the mBD‐1 promoter, leading to the induction of mBD‐1 expression in CECs." (PMID 40410944, 2025). "Collectively, these findings indicated that mBD‐1 induced following AhR activation plays a critical role in the attenuation of colitis in vivo." (PMID 40410944, 2025). "We next investigated whether AhR‐mediated induction of mBD‐1 plays a role in the regulation of colitis." (PMID 40410944, 2025). "However, when the mBD‐1 was blocked using an anti‐BD‐1 antibody, I3C failed to reverse the colitis‐associated dysregulation of gut microbiota and inflammation in female and male mice." (PMID 40410944, 2025). "Further focusing on AhR and mBD‐1, the data showed that the epithelial cells from anti‐CD40‐induced colitis mice exhibited decreased levels of AhR and mBD‐1 mRNA and protein expression when compared to the controls." (PMID 40410944, 2025). "Thus, in mice that failed to express AhR in CECs, I3C failed to induce mBD‐1 and as a result, they developed severe colitis." (PMID 40410944, 2025). "Interestingly, treatment of AhR∆IEC colitis mice with I3C did not result in an increase in mBD‐1 mRNA and protein expression when compared to WT mice with colitis and treated with I3C, in which there was an increase in mBD‐1." (PMID 40410944, 2025). "Interestingly, in these experiments, when we treated mice with mBD‐1 antibodies, I3C was not able to attenuate anti‐CD40‐mediated colitis." (PMID 40410944, 2025).
colorectal cancer (1 paper, 2023). A primary or metastatic malignant neoplasm that affects the colon or rectum. "Similar to human colorectal cancers, MALAT1 is slightly downregulated in the murine colonic polyps compared to healthy tissues, a pattern also observed in genes encoding known colorectal cancer tumor suppressor molecules, such as Mbd1 and Tmigd1." (PMID 37325561, 2023).
depression (1 paper, 2013). "Despite the fact that MBD1 is expressed ubiquitously, MBD1 deficiency in mice results largely in brain-associated phenotypes, including impaired adult neurogenesis, defective hippocampus-dependent learning, and susceptibility to depression." (PMID 23349673, 2013).
diabetic nephropathy (1 paper, 2023). "The relationship between SPI1, MBD1, and diabetic nephropathy needs further experimental verification." (PMID 37113991, 2023).
endometrial cancer (1 paper, 2014). Primary or metastatic malignant neoplasm involving the endometrium (mucous membrane that lines the endometrial cavity). "Our pipeline found MBD1 to be significantly mutated in binding sites in the endometrial cancer data set because of four somatic mutations affecting a binding site that recognizes methylated DNA." (PMID 24362839, 2014).
fungal infection (1 paper, 2020). "This is the first report utilizing the mBD-1 deletion mutation to model systemic fungal infection and to test antifungal therapy." (PMID 33007818, 2020).
influenza (1 paper, 2014). An acute viral infection of the respiratory tract, occurring in isolated cases, in epidemics, or in pandemics; it is caused by serologically different strains of viruses (influenzaviruses) designated A, B, and C, has a 3-day incubation period, and usually lasts for 3 to 10 days. "We have adopted intramuscular injection to deliver eukaryotic expression vector in this study, and all the results have shown that the recombinant mBD1/mBD3 expressed in the muscle manifest anti-influenza in the lung indeed." (PMID 24632574, 2014). "This recombinant mBD1-mBD3 might be developed into an agent for influenza prevention and treatment." (PMID 24632574, 2014).
keratitis (1 paper, 2016). A corneal disease that is characterized by inflammation of the cornea. "Although we did not see elevation of mBD3, nor test mBD1 after GLY treatment, we did observe reduction in IL-10 (mRNA), suggesting that a similar mechanism may be operative in the keratitis model." (PMID 27792814, 2016).
lupus (1 paper, 2017). "Other investigators described significantly higher mRNA levels of other enzymes (MBD1, MBD3, and MBD4), involved in the DNA methylation process, in patients with lupus." (PMID 28349196, 2017).
osteoarthritis (1 paper, 2021). A noninflammatory degenerative joint disease occurring chiefly in older persons, characterized by degeneration of the articular cartilage, hypertrophy of bone at the margins and changes in the synovial membrane. "Several chromatin modifying enzymes such as HAT1, KAT5, HDAC6, MBD1, and DNMT3A were downregulated at gene expression level in women with post-menopausal osteoporosis and osteoarthritis, with superior quantity and quality of bone being directly associated with HAT1, HDAC6, and MBD1 expression." (PMID 33805567, 2021).
Stroke (1 paper, 2017). Sudden impairment of blood flow to a part of the brain due to occlusion or rupture of an artery to the brain.
tumor (23 papers, 2008 to 2025). "While the previous experiments suggest a tumourigenic role, MBD1 is also found mutated in colon and lung cancer cell lines, supporting a tumour suppressor role." (PMID 28587163, 2017). "Although previous studies pointed to an oncogenic role of MBD1 in cancer, the evidence was that MBD1 was located on chromosome 18q21, a region of frequent loss of heterozygosity in several cancers, suggested that MBD1 might represent a candidate tumor suppressor gene." (PMID 25751725, 2015). "The role of MBD1 in tumor progression regulation has been reported in cancers of the pancreas, prostate, and leukemia." (PMID 35876658, 2022). "Taken together, these observations indicate a dual role of MBD1 both as a tumor suppressor and oncogene depending on the type of cancer." (PMID 31245293, 2019). "Our investigation indicated that MBD1 modulated EMT to participate in tumor progression, implying connections between MBD1 and resistance to Gem chemotherapy in GBC." (PMID 31516389, 2019). "In order to figure out the potential mechanism of MBD1 in the process of tumor inhibition, this study further screened genes related to MBD1 high expression in CRC gene expression profile." (PMID 28473981, 2017). "MBD1 expression is tumourigenic in pancreatic cancer cells but is suspected of a tumour suppressor role in other cancers." (PMID 28587163, 2017). "In this study, MBD1 had upregulated methylation and downregulated gene expression in advanced CRC and also had sustained upregulated methylation in the four stages of CRC, which suggested that MBD1 was a tumor suppressor gene for advanced CRC." (PMID 28473981, 2017). "MBD1 has been shown to bind the promoters of known tumor suppressor genes (e.g. p16, VHL and E-cadherin)." (PMID 24362839, 2014). "Furthermore, there was a negative correlation between miR-4429 expression and NR2F2-AS1 or MBD1 expression in tumor tissues." (PMID 32469064, 2020). "Moreover, MBD1 expression levels were significantly correlated with tumor differentiation and lymph node metastasis status." (PMID 31516389, 2019). "It has also been shown that MBD1 is involved in tumor development and progression." (PMID 31516389, 2019). "It has also been proven that MBD1 is involved in tumor development and progression." (PMID 31516389, 2019). "Methyl-CpG binding domain protein 1 (MBD1), a suppressor of gene transcription, may be involved in inactivation of tumor suppressor genes during tumorigenesis." (PMID 18445260, 2008). "For example, MBD1 may also act as a tumor suppressor in colorectal cancer." (PMID 31245293, 2019). "By modulating critical oncogenic processes such as epithelial–mesenchymal transition via its interactions with the MBD1-Twist-SIRT1 complex, SIRT1 not only influences tumor invasiveness but also impacts chemotherapy sensitivity." (PMID 39682281, 2024). "Analysis of two genes with common copy number alterations in mCRC (MBD1 and PLGC1) in plasma revealed high correlations between DELFI-TF or ddPCR tumor fraction and the copy number ratio at these regions in cfDNA (n = 79)." (PMID 39433569, 2024). "Key genes identified in this subtype included SLBP, MBD1, MINK1, DPH1, and CSNK1D, which are noted in existing literature for their roles in tumor malignancy and progression, thereby reinforcing the reliability of the ac4C score." (PMID 39648231, 2024). "Several DNA5mC regulators were found to be significantly overexpressed in tumor tissues, including DNMT1, DNMT3B, TET2, TET3, MBD1, and SMUG1." (PMID 36425533, 2022). "Further investigation illustrated that DNMT1/3A/3B, TDG, SMUG1, UNG, NEIL1, MDB3/4, ZBTB33, and UHRF1/2 were essentially upregulated in tumor samples, while TET2, MBD1, and MBD2 were downregulated in tumor samples." (PMID 35205097, 2022). "Another study reported that deletion of 18q21 chromosome where MBD1 was located occurred frequently in CRC, which suggested that genes in 18q21 chromosome zone might inhibit tumor growth in CRC." (PMID 28473981, 2017).
cancer (20 papers, 2008 to 2024). A tumor composed of atypical neoplastic, often pleomorphic cells that invade other tissues. "We also demonstrated that the expression of UHRF1, SMUG1, TDG, and MBD1/2/3 presented the most significant positive correlation with other regulators and might be the risk factors for carcinoma formation." (PMID 34552879, 2021). "In addition, MBD protein is known to regulate specific genes and to be involved in different cancer types, whereas the cancer types that MBD1 is associated with and the underlying mechanisms remain to be clarified." (PMID 25751725, 2015). "MBD1 is a major protein that binds methylated CpG to function the silencing effect of DNA methylation, and MBD1 is involved in the tumorigenesis of many human cancers." (PMID 35876658, 2022). "MBD1 depletion promotes cell invasion; the protein expression gradually decreases with the increase in cancer grade." (PMID 31245293, 2019). "Considering the complicated role of MBD1 in different cancers, herein, we first investigated its expression in GBC tissues and explored the correlation between its expression level and clinical prognosis." (PMID 31516389, 2019). "It is also of note that loss of “site-associated” genes such as WRN, NOTCH2, MBD1 and PI3KR1 had already been associated to development of human cancer." (PMID 29755661, 2018). "The mechanism of epigenetic regulation related to MBD1 offers much information about cancer diagnosis and drug development." (PMID 25751725, 2015). "As MBD1 has a distinct binding profile in specific cancer types, it has been used to identify novel methylated genes that are the potential targets for cancer therapy." (PMID 25751725, 2015). "Many of the proteins that were found to be down-regulated by the knock-down of MBD1 have been shown to be over-expressed in certain cancers." (PMID 18445260, 2008). "Instead, reagents targeting MBD proteins, such as MBD1, are better candidates for cancer therapy." (PMID 25751725, 2015). "Given that global hypomethylation is a characteristic of cancer, but being studied less than methylation of the promoter, studying the regulation system of MBD1 and hypomethylated DNA will be important in unveiling a novel regulatory mechanism in carcinogenesis." (PMID 25751725, 2015). "However, further elucidation of the expression of MBD1 in different cancer types or different stages is required." (PMID 25751725, 2015). "Furthermore, recent studies showed important roles of MBD1 in cancer and neuron development." (PMID 25751725, 2015). "Thus, MBD1 may have an important role in the silencing of tumor suppressor genes that are hypermethylated at their promoter CpG islands in cancer cells." (PMID 18445260, 2008). "Among epigenetic genes, DNA methylation related epigenetic modifiers, DNMT1, DNMT3A, MBD1, MBD4, TET1, TET2, and TET3, have been studied related to cancer." (PMID 32093698, 2020). "In this paper, we investigated the effect of mutations on DNA methylation modification genes such as DNMT1, DNMT3A, MBD1, MBD4, TET1, TET2, and TET3 through a pan-cancer analysis." (PMID 32093698, 2020). "CFP1 is closely related to MBD1, MBD2 on the 18q21 chromosome, a region that is often damaged in cancer." (PMID 31496919, 2019). "Hence, MBD1 expression may have different biological effect in different cancer." (PMID 28473981, 2017). "Further, epidermal growth factor receptor I (EGFR)-binding peptides are genetically attached to the MBD1 of DMA_21mCG, enabling its efficient endocytosis into EGFR-overexpressing cancer cells." (PMID 29229979, 2017). "In the cancer cell line C33a, MCAF1, MBD1, and SETDB1 co-localize at the H3K9me3-containing heterochromatin region." (PMID 23935871, 2013).
cancer (continued). "In cancer cells, MCAF1 is recruited to heterochromatin via the SIM through binding to SUMOylated MBD1." (PMID 23935871, 2013). "Therefore, we investigated the effect of mutations on DNA methylation modification genes such as DNMT1, DNMT3A, MBD1, MBD4, TET1, TET2 and TET3 through a pan-cancer analysis." (PMID 32093698, 2020). "EGFP expression increased in the cancer cells that were cotransfected with EGFP-MBD1 and siUHRF1, compared with cancer cells transfected with EGFP-MBD1 and the normal control siRNA (siNC) overall and in individual cancer cells, whereas expression of MBD1 itself did not change." (PMID 27507047, 2016). "However, the oncogenic role of MBD1 is not typical for all cancers." (PMID 31245293, 2019).